CREB3L1 (cAMP responsive element binding protein 3 like 1)
Diseases named in the same sentence as CREB3L1 in open-access papers (continued):
Sharing a sentence is not in itself a finding about the gene and the disease.
triple-negative breast carcinoma (10 papers, 2016 to 2024). An invasive breast carcinoma which is negative for expression of estrogen receptor (ER), progesterone receptor (PR), and human epidermal growth factor receptor 2 (HER2). "In contrast, CREB3L1 expression was repressed in high-grade tumors, and its loss was most frequently associated with triple negative breast cancers (TNBCs)." (PMID 26810754, 2016). "One study shows that CREB3L1 promotes triple negative breast cancer metastasis, whereas another study demonstrates that CREB3L1 inhibits triple negative breast cancer metastasis." (PMID 38233872, 2024). "In contrast, CREB3L1 is up-regulated in a metastatic subtype of triple-negative breast cancer cells that have activated both PERK signaling and the epithelial-to-mesenchymal transition program." (PMID 31334233, 2019). "Contradictory effect of CREB3L1 on triple negative breast cancer has been reported." (PMID 38233872, 2024). "CREB3L1 is a cAMP response element binding protein, which could predict the response of triple-negative breast cancer with doxorubicin chemotherapy." (PMID 38380081, 2024). "Interestingly, a retrospective study performed on biopsy samples analysis from triple negative breast cancer indicated that CREB3L1 levels in tumors responsive to doxorubicin chemotherapy were significantly higher than in those resistant to this treatment." (PMID 31334233, 2019). "For example, the metastasis suppressor genes CREB3L1 (cAMP-responsive element binding protein 3 like 1) and MTSS1 (metastasis suppressor 1) were recently found repressed in triple-negative breast cancer (TNBC)." (PMID 37369946, 2023). "The results showed that chemotherapy activated CREB3L1 and enhanced cell-surface GRP78 expression specifically in triple-negative breast cancer cells (TNBC), reducing their migration and metastatic potential." (PMID 33042795, 2020).
Osteopenia (9 papers, 2013 to 2024). Osteopenia is a term to define bone density that is not normal but also not as low as osteoporosis. "CREB3L1 deficient (Oasis-/-) mice displayed severe osteopenia characterized by diminished bone density." (PMID 38164349, 2024). "CREB3L1 termination codon mutations lead to severe osteopenia and reduced amounts of COL1α1, which is usually expressed in connective tissues." (PMID 35563641, 2022). "In mice CREB3L1 deficiency leads to severe osteopenia showing decreased bone density." (PMID 38164349, 2024). "The first evidence to support Creb3l1 in cell secretion was from Creb3l1 knockout mice that exhibit severe osteopenia due to reduced synthesis and secretion of bone matrix proteins." (PMID 35803572, 2022).
sarcoma (9 papers, 2015 to 2025). A usually aggressive malignant neoplasm of the soft tissue or bone. "To date, the biological functions of CREB3L1 mutations are mostly investigated in modulating osteogenesis process, and only few studies have reported that EWSR1-CREB3L1 fusion mutation in sarcomas." (PMID 36171879, 2022). "Nine fusion genes were specific to particular histotypes, including SYT::SSX fusion in synovial sarcoma, EWSR1::FLI1 fusion in ES, EWSR1::NR4A3 fusion in EMC, BCOR::CCNB3 fusion in sarcoma with BCOR genetic alterations, and EWSR1::CREB3L1 fusion in sclerosing epithelioid fibrosarcoma." (PMID 40755265, 2025). "Normal and tumor tissues with similar CREB3L1 expression include ESCA esophageal cancer, GBM glioblastoma multiforme, HNSC head, and neck squamous cell carcinoma, LUAD lung adenocarcinoma, SARC sarcoma, THCA papillary thyroid carcinoma, THYM thymoma, UCEC uterine corpus endometrial carcinoma." (PMID 34996478, 2022).
bladder cancer (8 papers, 2016 to 2025). "In agreement with this idea, epigenetic silencing of CREB3L1 was associated with the cell dedifferentiation process in some forms of breast and bladder cancer development." (PMID 35455992, 2022). "who found that CREB3L1 gene expression was downregulated in bladder cancer and that the loss of expression was associated with DNA methylation of the gene." (PMID 26810754, 2016). "Epigenetic downregulation of CREB3L1 mRNA expression by DNA methylation is associated with increased tumor grade and aggressive phenotype in bladder cancer." (PMID 26810754, 2016). "A similar pattern is observed in bladder cancer progression, where CREB3L1 is localized in the nucleus of less aggressive tumors but remains in the cytoplasm of late-stage tumors." (PMID 40427627, 2025). "The expression of CREB3L1 is downregulated in bladder cancer tissues due to promoter hypermethylation, its protein deletion is often found in the nuclei of bladder cancer cells with aggressive phenotype." (PMID 38164349, 2024). "In breast and bladder cancer, CREB3L1 is highly methylated, and CREB3L1 expression is inversely correlated with tumor grade, indicating that it acts in a tumor-suppressive manner." (PMID 37629188, 2023). "cAMP responsive element binding protein 3 like 1 (CREB3L1), a member of the unfolded protein response, has recently been identified as a metastasis suppressor in both breast and bladder cancer." (PMID 29531016, 2018). "In some cases, studies have shown that aggressive phenotypes of breast and bladder cancer have low Creb3l1 expression resulting from Creb3l1 promoter hypermethylation." (PMID 29311806, 2017). "Similar subcellular localization patterns of CREB3L1 are observed during bladder cancer progression, suggesting a common function for CREB3L1 in at least these two cancer types." (PMID 26810754, 2016). "CREB3L1 (cAMP-responsive element-binding protein 3-like protein 1), a member of the unfolded protein response, has recently been identified as a metastasis suppressor in both breast and bladder cancer." (PMID 26810754, 2016). "Re-expression of CREB3L1 in high-grade invasive bladder cancer cells reduced cell migration and the growth of colonies in soft agar, supporting a role for CREB3L1 as a tumor/metastasis suppressor in bladder cancer." (PMID 35802566, 2022). "Hypermethylation of CREB3L1 at its promoter, as well as within coding and non-coding regions, has been established in TNBC as well as human bladder cancer." (PMID 40427627, 2025). "An overlap in the hypermethylated sites has been identified between TNBC and bladder cancer patients, spanning from +197 bases to +554 bases relative to the transcription start site (TSS) of CREB3L1." (PMID 40427627, 2025). "This may suggest that ROR1 plays a role in the epigenetic silencing of CREB3L1 in TNBC and potentially in bladder cancer as well." (PMID 40427627, 2025).
glioblastoma (6 papers, 2013 to 2024). The most malignant astrocytic tumor (WHO grade IV). "Downregulated CREB3L1 expression and functionally mutated CREB3L1 facilitate glioblastoma proliferation, correspondingly recovery of CREB3L1 hinders glioblastoma formation." (PMID 38164349, 2024). "Owing to the high methylation status of CREB3L1 promoter, a proportion of tumors displayed low CREB3L1 expression, target removal of promoter hypermethylation hampers glioblastomas formation in nude mice." (PMID 38164349, 2024).
breast tumors (5 papers, 2016 to 2024). "Normally, low and medium grade breast tumors show increased CREB3L1 expression, while in advanced and metastatic breast cancers the expression of CREB3L1 was suppressed attributing to the preferential methylation of CpG island." (PMID 38164349, 2024). "Overall, luminal A (median 8.8) and HER2 (median 8.9) breast tumors showed a small but significant increase in CREB3L1 expression as compared to normal breast tissue (median 8.2) (p < 0.0001)." (PMID 35802566, 2022). "Consistently, expression of CREB3L1 was highest in breast tumors that have both active PERK signaling and EMT signaling." (PMID 29057869, 2017). "Low-grade and medium-grade breast tumors had increased CREB3L1 expression, when compared to normal breast tissue samples." (PMID 26810754, 2016). "An IHC analysis was carried out to characterize CREB3L1 protein expression and subcellular localization in 97 human breast tumor sections." (PMID 26810754, 2016). "In human breast tumors, CREB3L1 mRNA expression was upregulated in low and medium-grade tumors, most frequently of the luminal and HER2 amplified subtypes." (PMID 26810754, 2016). "As has been noted in bladder cancer tumors, the 41 breast tumor samples that expressed CREB3L1 protein showed two main CREB3L1 localization patterns." (PMID 26810754, 2016). "We found that methylation of two regions (numbers 2 and 3), within the first CpG island, negatively correlated with CREB3L1 mRNA expression, and they were less methylated in breast tumor samples." (PMID 26810754, 2016). "Methylation in each of these regions positively correlated with CREB3L1 mRNA expression and all were significantly more methylated in breast tumor samples compared to normal breast tissue." (PMID 26810754, 2016). "Moreover, patients with reduced CREB3L1 expression have a shorter relapse-free survival as compared to patients with breast tumors expressing CREB3L1, particularly for the luminal A (p = 8.8 x 10−6) and TNBC (p = 0.038) subtypes." (PMID 35802566, 2022). "We have assessed human breast tumor samples of various grades for the expression of CREB3L1." (PMID 26810754, 2016). "In contrast, high-grade breast tumors had reduced CREB3L1 expression." (PMID 26810754, 2016). "Overall, CREB3L1 was lost in 31 % (67/213) of the human breast tumor samples analyzed, but importantly CREB3L1 was lost from a much larger fraction of the high-grade (8 and 9) metastatic breast tumors (51 % of grade 8 and 73 % of grade 9 breast tumors; p = 0.001)." (PMID 26810754, 2016). "The analysis of CREB3L1 DNA methylation in breast tumors in the TCGA database, also with suggested CpG sites 238 and 259 (i.e., region number 2), were usually more methylated in tumors with low CREB3L1 mRNA expression, but were generally less methylated in breast tumors than in normal breast tissue." (PMID 26810754, 2016). "In low-grade breast tumors CREB3L1 is predominantly a nuclear protein, consistent with its processing into the mature form and translocation into the nucleus as part of the cellular stress response to activate CREB3L1." (PMID 26810754, 2016). "CREB3L1 mRNA levels were increased in breast tumors, particularly for early-stage tumors." (PMID 26810754, 2016). "High-grade breast tumors that still express CREB3L1 typically have mainly cytoplasmic protein localization, which likely would prevent CREB3L1-mediated transcriptional repression of target genes that promote cell growth, survival, migration, invasion, angiogenesis and metastasis." (PMID 26810754, 2016). "In contrast, high-grade (8 and 9) breast tumors had reduced CREB3L1 expression (p = 0.001)." (PMID 26810754, 2016). "We determined the relative methylation for each region in normal versus breast tumor samples to assess which regions might be involved in regulating CREB3L1 expression changes." (PMID 26810754, 2016).
breast tumors (continued). "Importantly, the low-grade breast tumors more frequently had nuclear CREB3L1 protein, in contrast to the high-grade breast tumors in which CREB3L1 was cytoplasmic (p = 0.003, Mann–Whitney U test)." (PMID 26810754, 2016). "Region number 2 showed the largest significant difference in methylation between normal breast and breast tumors, suggesting that changes in methylation in this region may have the largest influence on CREB3L1 mRNA expression." (PMID 26810754, 2016). "An immunohistochemistry analysis revealed that low-grade breast tumors frequently had nuclear CREB3L1 protein, in contrast to the high-grade breast tumors in which CREB3L1 was cytoplasmic, suggesting that differential localization may also regulate CREB3L1 effectiveness in metastasis suppression." (PMID 26810754, 2016). "In support of this, high levels of CREB3L1 DNA methylation and low levels of CREB3L1 mRNA expression were more frequently observed in TNBC cell lines and breast tumor samples." (PMID 26810754, 2016). "For example, regions number 16, 19 and 20 (near the 3′ end of intron 1) all had increased methylation in breast tumor samples as compared to normal breast tissue, raising the possibility that methylation in these regions could influence CREB3L1 mRNA expression." (PMID 26810754, 2016). "The majority of grade 8 (51 %) and grade 9 (73 %) breast tumors lacked CREB3L1 mRNA expression." (PMID 26810754, 2016).
osteosarcoma (5 papers, 2014 to 2024). A usually aggressive malignant bone-forming mesenchymal neoplasm, predominantly affecting adolescents and young adults. "The genes of four TFs (DDIT3, SP7 and CREB3L1) were significantly activated in C5_osteoblastic OS cells, and these TFs have been shown to be expressed in osteosarcoma in previous studies." (PMID 34367994, 2021). "This analysis revealed that osteosarcoma, malignant fibrous histiocytoma and ovarian mucinous adenocarcinoma have the highest levels of CREB3L1 mRNA." (PMID 26110425, 2015). "Using immunohistochemistry (IHC) and bioinformatics analyses, we showed that cancers known to be responsive to doxorubicin treatment such as diffuse large B-cell lymphoma (DLBCL) and osteosarcoma expressed higher levels of CREB3L1 than those known to be resistant to the treatment such as RCC." (PMID 26110425, 2015). "Doxorubicin is used as the standard treatment for cancers that express the highest levels of CREB3L1 such as osteosarcoma and malignant fibrous histiocytoma but is not generally used to treat those that express the lowest levels of CREB3L1 such as RCC." (PMID 26110425, 2015).
thyroid cancer (5 papers, 2022 to 2025). "Several transcription factors including E2F7, FOXM1, NFYB, and CREB3L1 were significantly associated with the OS of thyroid cancer patients and may be the main regulators of ATC progression." (PMID 36192735, 2022). "In thyroid cancer, CREB3L1 mediates IL‐1α production to activate α‐SMA‐positive fibroblasts and downstream ECM signalling." (PMID 39902627, 2025). "These implied that CREB3L1 is critical for thyroid cancer cell fate determination and ATC progression." (PMID 38164349, 2024). "Studies have shown that α-SMA-positive CAFs were activated through CREB3L1-mediated IL-1α production, the presence of CAF inhibits thyroid cancer growth and metastasis after CREB3L1 knockdown." (PMID 37719863, 2023). "IHC staining of CREB3L1 in an independent cohort of 234 thyroid cancer tissues showed that high expression of CREB3L1 was significantly correlated with shorter progression-free survival (P = 0.000229)." (PMID 36192735, 2022). "Reportedly, elevated CREB3L1 expression can indicate a higher risk of PTC recurrence and potentially plays a role in thyroid cancer dedifferentiation." (PMID 36192735, 2022). "This revealed that CREB3L1 was specifically up regulated in ATC tissues and negatively associated with overall survival of patients with thyroid cancer." (PMID 36192735, 2022). "The multivariate Cox regression analysis indicated that both TNM staging and high CREB3L1 expression were accurate OS predictors in thyroid cancer patients." (PMID 36192735, 2022). "According to the univariate analysis, thyroid cancer patients with elevated CREB3L1 expression (hazard ratio [HR] = 4.831, 95% confidence interval [CI]: 1.754–13.3, P = 0.00231) were more likely to die than those with lowered CREB3L1 expression." (PMID 36192735, 2022). "Since the role of KPNA2 in thyroid cancer is rarely reported, our findings shed light on the KPNA2-mediated ECM remodeling in ATC by transporting CREB3L1 into the nucleus." (PMID 36192735, 2022). "Mechanistically, CREB3L1 overexpression can facilitate the dedifferentiation of papillary thyroid cancer cells into ATC cells, and promote thyroid cancer progression by regulating EMT process and the mTOR signaling pathway." (PMID 36171879, 2022).
anaplastic thyroid cancer (4 papers, 2022 to 2025). "Previous studies have shown that KPNA2 enhances extracellular matrix (ECM) signalling by mediating the nuclear translocation of CREB3L1, thereby promoting the growth and metastasis of anaplastic thyroid carcinoma." (PMID 40830912, 2025). "Nevertheless, in anaplastic thyroid cancer (ATC), where cells exhibit stem cell–like properties and NIS gene expression is totally silenced, copy number gain of the specific region of the Chr11 that include CREB3L1 gene and high levels of CREB3L1 expression were detected." (PMID 35455992, 2022).
hepatoma (4 papers, 2012 to 2024). "To analyze proteolytic activation of CREB3L1, we fractionated human hepatoma Huh7 cells into membrane and nuclear fractions, and used an antibody reacting against the NH2-terminal domain of CREB3L1 to examine the cleavage of CREB3L1 through immunoblot analysis." (PMID 23256041, 2012). "We previously reported that doxorubicin inhibited proliferation of Huh7 cells (a line of human hepatoma cells) transfected with a control shRNA but not those stably transfected with a shRNA targeting CREB3L1 when these cells were cultured in vitro." (PMID 26110425, 2015).
liver fibrosis (4 papers, 2021 to 2025). "In addition, CREB3L1 is involved in diverse fibrotic diseases, including renal fibrosis, liver fibrosis, hypertrophic scar, and keloids." (PMID 38164349, 2024). "Overall, this suggests that CREB3L1 might be a promising novel drug target for liver fibrosis, with established translatability in key rodent models, and modulation of it is likely to result in effective anti-fibrotic activity." (PMID 34588551, 2021).
lung squamous cell carcinoma (4 papers, 2015 to 2025). "At the other end of the spectrum, we identified chondrosarcoma, RCC, squamous cell lung cancer, brain cancers and small cell lung carcinoma as the cancers with the lowest levels of CREB3L1 mRNA." (PMID 26110425, 2015). "Importantly, we identified a large group of cancer types where low CREB3L1 expression is prevalent, including lung squamous cell carcinoma, melanoma and cancers of the kidney (clear cell), bladder, colon, liver, adrenal gland, rectum and cervix." (PMID 26810754, 2016). "Furthermore, as CREB3L1 silencing has been observed in lung squamous cell carcinoma, colon, adrenal gland, rectum, cervix, and liver cancers, the findings from this study may have broader implications beyond TNBC." (PMID 40427627, 2025).
metastatic disease (4 papers, 2017 to 2025). "Further, the ability to identify the subset of luminal A (7%) and TNBCs (75%) that are CREB3L1-deficient provides opportunities to stratify patients that would benefit from additional treatments to treat their more metastatic disease." (PMID 35802566, 2022). "Reduced CREB3L1 expression is associated with higher tumor grade and more advanced metastatic disease." (PMID 35802566, 2022). "In contrast, mice injected with MDAMB231/CREB3L1-KO and given chemotherapy showed multifocal parenchymal metastases and large metastatic tumors with increased pleomorphism and intravascular invasion." (PMID 33042795, 2020). "Given the lack of a functional assessment of CREB3L1+ CB cells in metastatic OS, the present findings only revealed that CREB3L1+ CB cells were enriched in metastatic tumors." (PMID 40831537, 2025).
papillary thyroid carcinoma (4 papers, 2016 to 2022). "CREB3L1 knockdown dramatically attenuated invasion of ATC cells, whereas overexpression of CREB3L1 facilitated the invasion of papillary thyroid carcinoma (PTC) cells." (PMID 36192735, 2022).